NR0B2 (nuclear receptor subfamily 0 group B member 2)
Description:
Transcriptional regulator that acts as a negative regulator of receptor-dependent signaling pathways. Specifically inhibits transactivation of the nuclear receptor with which it interacts. Inhibits transcriptional activity of NEUROD1 on E-box-containing promoter by interfering with the coactivation function of the p300/CBP-mediated transcription complex for NEUROD1. Essential component of the liver circadian clock which via its interaction with NR1D1 and RORG regulates NPAS2-mediated hepatic lipid metabolism (By similarity). Regulates the circadian expression of cytochrome P450 (CYP) enzymes (By similarity). Represses: NR5A2 and HNF4A to down-regulate CYP2C38, NFLI3 to up-regulate CYP2A5, BHLHE41/HNF1A axis to up-regulate CYP1A2, CYP2E1 and CYP3A11, and NR1D1 to up-regulate CYP2B10, CYP4A10 and CYP4A14 (By similarity).
Synonyms: SHP; SHP1
Tractability: Small molecule: a structure with a bound ligand is known; a high-quality ligand is known; it belongs to a druggable protein family. PROTAC: a small molecule that binds it is known.
Target class: Nuclear hormone receptor subfamily 0 group B member 2; Nuclear hormone receptor subfamily 0; Transcription factor; Nuclear hormone receptor subfamily 0 group B; Nuclear receptor
Chemical probes: ML287, ML288
Safety:
Unwanted effects reported when the protein is acted on. In parentheses: how it was acted on, where the effect was seen, and who reports it.
Increased, Liver Steatosis (activation; source: AOP-Wiki)
Gene: Protein-coding gene on chromosome 1 (26,911,489 to 26,913,975, reverse strand). Ensembl gene ENSG00000131910.
Subcellular location: Nucleus; Cytoplasm
Subcellular location (Human Protein Atlas): Nucleoplasm; Vesicles
Pathways (Reactome):
Gene expression (Transcription): Nuclear Receptor transcription pathway
Gene Ontology:
Molecular function: protein binding; protein domain specific binding; protein homodimerization activity; transcription corepressor activity; transcription regulator inhibitor activity; nuclear receptor binding; nuclear retinoic acid receptor binding; nuclear retinoid X receptor binding; nuclear thyroid hormone receptor binding; peroxisome proliferator activated receptor binding; protein-containing complex binding
Biological process: circadian rhythm; negative regulation of gene expression; positive regulation of DNA-templated transcription; positive regulation of gene expression; cholesterol metabolic process; circadian regulation of gene expression; negative regulation of DNA-templated transcription; negative regulation of transcription by RNA polymerase II; animal organ regeneration; positive regulation of insulin secretion; response to ethanol; response to glucose
Cellular component: chromatin; cytoplasm; nucleoplasm; nucleus; transcription repressor complex; protein-containing complex
Genetic constraint (gnomAD): Loss-of-function variants: 17 observed, 19.03 expected, observed/expected ratio (o/e) 0.89, 90% interval 0.61 to 1.34. The upper end of that interval is the gene's LOEUF score, 1.34, which puts it in group 5 of 6, group 1 being the genes least tolerant of losing a copy. Missense variants: 312 observed, 341.24 expected, observed/expected ratio (o/e) 0.91, 90% interval 0.83 to 1. Synonymous variants: 116 observed, 139.7 expected, observed/expected ratio (o/e) 0.83, 90% interval 0.71 to 0.97.
Homologues: Orthologues: chimpanzee NR0B2 (99% identical), macaque NR0B2 (98% identical), guinea pig NR0B2 (88% identical), rabbit NR0B2 (85% identical), dog NR0B2 (84% identical), pig NR0B2 (82% identical), mouse Nr0b2 (79% identical), rat Nr0b2 (79% identical), zebrafish nr0b2a (51% identical), tropical clawed frog nr0b2 (38% identical), zebrafish nr0b2b (36% identical). Paralogues in human: NR0B1 (37% identical).
Diseases named in the same sentence as NR0B2 in open-access papers:
NR0B2 is named in the same sentence as 121 diseases in open-access papers, as found by Europe PMC text mining. Sharing a sentence is not in itself a finding about the gene and the disease. The quoted sentences say what the papers report.
Hepatic steatosis (29 papers, 2012 to 2026). Steatosis is a term used to denote lipid accumulation within hepatocytes. "From this approach, we identified strong enrichment of genes induced by B2D with metabolic transcription factor knockouts that cause fatty liver disease, such as Ppara, Nr1h4, and Nr0b2." (PMID 37417957, 2023).
cholestasis (18 papers, 2012 to 2026). Impairment of the bile flow caused by obstruction within the liver, or outside the liver in the bile duct system. "Consistently, combined loss of Nr1h4 and Nr0b2 in mice results in juvenile onset cholestasis that progresses to HCC." (PMID 41460563, 2025). "Mutations and reduction in Nr1h4, and Nr0b2 transcript levels have been noted in cholestasis (reduced bile flow and subsequent increase in hepatic and serum bile acids [(BA])), fatty liver disease, and liver cancer." (PMID 41460563, 2025). "Important genes known to play a role in cholestasis such as ABCB4 (MDR3), ABCB11 (BSEP) and NR0B2 (SHP) were downregulated in human PCLS exposed to bile acids and cholestatic drugs." (PMID 27344345, 2017).
Obesity (18 papers, 2007 to 2025). Accumulation of substantial excess body fat. "Mutations in the small heterodimer partner (SHP, NR0B2) have been associated with mild obesity in several human populations." (PMID 25951943, 2015). "Heterozygous loss-of-function mutations in NR0B2 in OMIM (*604630) are associated with mild early-onset obesity, whereas truncating mutations in GCKR may be linked to increased levels of blood triglycerides." (PMID 35207755, 2022). "The network shows that RXRA interacts with proteins related to a tumor (THRA related to pituitary adenome) and those related to certain diseases caused by abnormalities in lipid metabolism (e.g., NR0B2 related to obesity, PPARA to hyperapobetalipoproteinemia, and PPARGC1A to lipodystrophy)." (PMID 17705877, 2007).
liver cancer (17 papers, 2011 to 2025). An epithelial or non-epithelial malignant neoplasm that arises from the liver. "NR0B2 has been associated with only 4 alerts that pertained to protection against viral hepatitis-related liver cancers and the repression of bile acid biosynthesis (i.e., via downregulation of Cyp7a1)." (PMID 39065726, 2024). "In liver cancer patients, higher NR0B2 expression is associated with favorite relapse-free and progression-free survival, especially in Asian male patients with viral infection history." (PMID 34055653, 2021). "Higher NR0B2 expression is associated with fewer disease relapse and progression in liver cancer patients and is also associated with a favorite overall survival prognosis in human breast cancers, lung adenocarcinomas, liposarcomas, and eye uveal melanomas." (PMID 34055653, 2021). "Here, we report that mice lacking bile acid (BA) regulators, Farnesoid X Receptor (FXR also termed NR1H4) and Small Heterodimer Partner (SHP also termed NR0B2), recapitulate the sex difference in liver cancer risk." (PMID 41460563, 2025). "More importantly, NR1H4 and NR0B2 transcript expression was reduced in liver cancer patients, underscoring the clinical relevance of this DKO mouse model." (PMID 41460563, 2025). "It has been reported that NR0B2 expression affects the innate immune response in liver cancer, where a partial but significant correlation between lower NR0B2 expression levels and a higher tumor infiltration of B cells and CD8+ T cells has been found." (PMID 39336801, 2024). "It was reported that NR0B2 gene expression was significantly reduced in liver and kidney cancers and that overexpression of NR0B2 protein suppresses liver cancer development, indicating it is a tumor suppressor." (PMID 34055653, 2021). "NR0B2 gene expression is altered mainly in most human malignancies and significantly reduced in liver cancers." (PMID 34055653, 2021). "This study found an interesting correlation of NR0B2 expression with over survival in liver cancer patients with viral hepatitis history (HR = 0.52, p = 0.0416), which was more significant in Asian male patients (HR = 0.33, p = 0.0157)." (PMID 34055653, 2021). "Further investigation is needed to verify the clinical significance of NR0B2 expression in protecting viral infection-related liver cancer development and progression." (PMID 34055653, 2021). "Consistently, PI3K inhibition significantly enhanced NR0B2 expression at the transcription level in human liver cancer HepG2 and Huh7 cells." (PMID 34055653, 2021). "It was reported that the NR0B2 gene promoter region is hypermethylated in human liver cancer tissues and cell lines, and treatment of liver cancer cells with DNA demethylation agent 5-Aza-2′-deoxycytidine vastly enhanced NR0B2 expression." (PMID 34055653, 2021). "The orphan nuclear receptor NR0B2 was reported to suppress liver cancer development in a mouse model, and its expression levels were reduced in liver cancer tissues and cell lines due to hypermethylation within its promoter region." (PMID 34055653, 2021). "Patient stratify analysis revealed that NR0B2 expression is a favorite factor in liver cancer patients of Asian males with viral infection history." (PMID 34055653, 2021). "Kinase-specific inhibitors for MAPK kinase (PD98059 and U0126), JNK kinase (SP600125), p38 kinase (SB203580), and PI3K (LY294002) were used to treat liver cancer cells HepG2 and Huh7, followed by qPCR-based NR0B2 mRNA measurement." (PMID 34055653, 2021). "To explore the clinical significance of NR0B2 gene expression in human cancers, we analyzed the correlation between patient survival and NR0B2 gene expression, with an emphasis on liver cancers." (PMID 34055653, 2021). "Multiple cancer databases were utilized to explore NR0B2 gene expression profiles crossing a variety of human cancers, including liver cancers, on several publicly assessable bioinformatics platforms." (PMID 34055653, 2021).
liver cancer (continued). "There is a paucity of NR0B2 expression from human cancer specimens, and so far, only two reports showed NR0B2 downregulation in 10 cases of liver cancers (HCC) and 24 cases of renal cancers (RCC)." (PMID 34055653, 2021). "NR0B2 gene is predominantly expressed in liver tissue crossing human major organs or tissues, but it is significantly downregulated in liver cancers." (PMID 34055653, 2021). "Especially, NR0B2 expression is a favorite survival factor in Asian male patients with viral infection-related liver cancers." (PMID 34055653, 2021). "Evidence suggests that NR0B2 plays an important suppressing role in the development of liver cancer." (PMID 31851620, 2019). "NR0B2 is a prognosis factor for patient survival in liver cancers." (PMID 34055653, 2021). "Considering a previous report showing ERK activity as a critical factor for NR0B2 protein stability in HepG2 cells, we hypothesize that in human liver cancer cells, ERK activity might be essential for both NR0B2 gene expression and protein stability." (PMID 34055653, 2021). "Interestingly, in this study, we found that NR0B2 expression negatively correlated with the expression levels of two PI3K genes PIK3CA and PIK3CG, while PI3K inhibition significantly enhanced NR0B2 expression in liver cancer cells." (PMID 34055653, 2021). "It is feasible that NR0B2 expression might serve as a biomarker for anti-PI3K therapeutic responsiveness in human liver cancers." (PMID 34055653, 2021). "The activation of FXR target, SHP (NR0B2) by FXR agonists was also detected in liver cancer cells." (PMID 35006466, 2021). "We previously showed that the combined deletion of nuclear receptors, Farnesoid X Receptor (FXR, NR1H4), and Small Heterodimer Partner (SHP, NR0B2) resulted in spontaneous liver cancer in the year-old male mice." (PMID 41460563, 2025). "In this study, we re-analyzed several public datasets for NR0B2 expression patterns in human benign and malignant tissues and investigated the involvement of MAPK and PI3K pathways in human liver cancer cells." (PMID 34055653, 2021). "Correlation analysis discovered that NR0B2 expression is negatively correlated with PI3K pathway genes PIK3CA and PIK3CG in liver cancer tissues." (PMID 34055653, 2021). "NR0B2 is also negatively correlated with PIK3CA and PIK3CG genes in liver cancer tissues, and PI3K inhibition enhances NR0B2 gene expression in liver cancer cells." (PMID 34055653, 2021). "Although 15-month-old individual Nr1h4 knockout and individual Nr0b2 knockout mice were previously shown to develop liver cancer, unlike the DKO mice, their incidence does not show 100% penetrance nor sex differences." (PMID 41460563, 2025). "Although DKO female mice do not develop liver cancer, it is pertinent to note that they lack Nr1h4 and Nr0b2 gene expression, display chronic cholestasis similar to their male counterparts, and hence the global gene changes associate with poor OS." (PMID 41460563, 2025). "Gene expression analysis determined that the ERK pathway was essential for basal and GW4064-induced NR0B2 expression while the PI3K/AKT pathway only prevented NR0B2 expression at the basal but not bile acid stimulation condition in liver cancer cells." (PMID 34055653, 2021). "MAPK and PI3K oppositely modulate NR0B2 expression, and NR0B2 gene upregulation might serve as a therapeutic responsiveness factor in anti-PI3K therapy for liver cancer." (PMID 34055653, 2021). "NR0B2 expression is conversely correlated with tumor-infiltrating B-cells, CD8+ T cells, and dendritic cells, as well as PIK3CA and PIK3CG gene expression in liver cancer tissues." (PMID 34055653, 2021). "In addition, NR0B2 expression negatively correlated with immune infiltration and PIK3CA and PIK3CG gene expression in liver cancer tissues." (PMID 34055653, 2021).
liver cancer (continued). "In this study, we report that, unlike the males, female Nr1h4-/-, Nr0b2-/- (Fxr-/-, Shp-/-) double knockout (DKO) mice exhibit protection against tumorigenesis and thus mimic the sexual dimorphism in liver cancer incidence observed in clinics." (PMID 41460563, 2025). "This study discovered a negative correlation of NR0B2 expression with tumor-infiltrating lymphocytes, including B cells, CD8+ T cells, and dendritic cells in liver cancer tissues." (PMID 34055653, 2021).
liver fibrosis (17 papers, 2011 to 2024). "NR0B2 upregulation in PSC liver was independent of gender, age, body mass index, liver fibrosis, and PSC complications." (PMID 39130146, 2023).
diabetes (12 papers, 2012 to 2025). "Since NR0B2 is involved in lipid and glucose metabolisms and inflammation, dysfunctionality in these processes may be associated with the risk of rapid mood cycling, this coincides with the higher rates of rapid cycling observed in BD patients with diabetes mellitus or insulin resistance." (PMID 34916903, 2021).
hepatocellular carcinoma (12 papers, 2009 to 2024). A malignant tumor that arises from hepatocytes. "Regarding the mechanisms involved, in vitro studies suggest that the overexpression of NR0B2 can inhibit hepatocellular carcinoma (HCC) lesions’ formation and tumor growth, potentially through SHP’s (the protein corresponding to NR0B2) regulation of cyclin D1." (PMID 39336801, 2024).
adrenal hypoplasia (8 papers, 2014 to 2025). "LRH-1 is active constitutively and its transcriptional activity is repressed by orphan receptors like the Small Heterodimer Partner (SHP/NR0B2) and the dosage-sensitive sex reversal-adrenal hypoplasia congenital gene on the X chromosome (DAX-1)." (PMID 26421305, 2015).
breast carcinoma (6 papers, 2011 to 2022). "Higher NR0B2 expression is significantly associated with a favorite overall survival, metastasis-free and relapse-free survival in breast cancer patients." (PMID 34055653, 2021). "NR0B2 activation by CD437 exerts pro-apoptotic actions in ER−/MDA-MB-468 breast-cancer cells via transcriptional mechanisms." (PMID 26894976, 2016). "In conclusion, NR0B1 and NR0B2 are endowed with onco-suppressive properties in breast-cancer." (PMID 26894976, 2016). "Mammary-glands contain low NR0B1-mRNA and NR0B2-mRNA levels and NR0B1-mRNA is down-regulated in all PAM50 breast-cancer types." (PMID 26894976, 2016).
gastric cancer (5 papers, 2010 to 2024). A primary or metastatic malignant neoplasm involving the stomach. "Prognostic analyses showed that a low expression of NR0B2 is a risk factor for the poor prognoses of gastric cancer." (PMID 39336801, 2024). "Our study confirms the causal relationship between the expression of NR0B2 and the risk of gastric diseases, and highlights its role in the progression of gastric cancer." (PMID 39336801, 2024). "In this pathway, we have also found a downregulation of CCL19, a tumor suppressor that reduces proliferation, migration and invasion in gastric cancer, and NR0B2, whose downregulation in renal carcinoma is associated with development and progression of cancer." (PMID 34012923, 2021). "MR analyses revealed that NR0B2 expression is associated with a risk of gastric diseases (NR0B2 vs. gastric cancer, p = 0.006, OR: 0.073, 95%CI: 0.011–0.478; NR0B2 vs. gastric ulcer, p = 0.03, OR: 0.991, 95%CI: 0.984–0.999; NR0B2 vs. other gastritis, p = 0.006, OR:3.82, 95%CI: 1.468–9.942)." (PMID 39336801, 2024). "NR0B2 appears to be a potential target for drug development for gastric cancer, but we also need to be aware that such drugs may cause side effects such as gastritis." (PMID 39336801, 2024). "Also, there are many risk factors for gastric cancer, and NR0B2 is only one of them." (PMID 39336801, 2024). "While we observed that a decreased NR0B2 expression is a risk factor for gastric cancer, it should be noted that in some individuals with gastric cancer, NR0B2 expression is increased." (PMID 39336801, 2024). "Bioinformatics analysis revealed that NR0B2 expression levels were reduced in gastric cancer and increased in gastritis." (PMID 39336801, 2024). "Given that NR0B2 also plays a key role in cholesterol regulation, we tried to extract variables related to NR0B2 from cholesterol and conducted a two-sample Mendelian randomization analysis of gastric cancer." (PMID 39336801, 2024). "Our GESA shows NR0B2′s involvement in the NRF2 antioxidant pathway in both gastric cancer and gastritis." (PMID 39336801, 2024). "The differences in the correlations found in gastric cancer and gastritis further indicate that NR0B2 plays different roles in these diseases." (PMID 39336801, 2024). "The GO analysis revealed that NR0B2 and its co-expressed genes in gastric cancer are predominantly involved in lipid metabolism and oxidation reactions." (PMID 39336801, 2024). "This consistency across multiple databases reinforces the conclusion that NR0B2 expression is diminished in gastric cancer." (PMID 39336801, 2024). "The Oncomine database has more than 30 datasets showing a significant reduction of NR0B2 gene expression in human cancers, including liver, renal, lung, and gastric carcinomas." (PMID 34055653, 2021). "Although there was no overlap between the merged genes in gastric cancer and gastritis (except for NR0B2), the GO results suggest that NR0B2 and its co-expressed genes participate in lipid metabolic and oxidation-related processes in gastric cancer and gastritis." (PMID 39336801, 2024). "We found that the high expression of NR0B2 is a favorable prognostic factor for gastric cancer and may reduce its incidence, potentially through Treg-mediated inflammatory regulation." (PMID 39336801, 2024). "This suggests that NR0B2 plays different roles in gastric cancer and gastritis." (PMID 39336801, 2024). "We assessed NR0B2 expression using data from the TNMplot website, GSE138631&GSE26942 and GSE179252 for gastric cancer, and GSE233973 for gastritis." (PMID 39336801, 2024). "This can explain why NR0B2 is not always decreased in gastric cancer." (PMID 39336801, 2024). "This indicates that although cholesterol might have an impact on gastric cancer, it is unlikely to be regulated by NR0B2." (PMID 39336801, 2024).